OR5AN1 (olfactory receptor family 5 subfamily AN member 1)
Description:
Odorant receptor for musk, which specifically recognizes muscone, musk xylol, and musk ketone. Ligand-binding causes a conformation change that triggers signaling via G(s)-class of G alpha protein GNAL, activating adenylyl cyclase (Probable).
Synonyms: OR11-244
Tractability: Antibody: UniProt places it where antibodies can reach, with high confidence; its Gene Ontology location is reachable by antibodies, with high confidence; UniProt predicts a signal peptide or a membrane-spanning region.
Gene: Protein-coding gene on chromosome 11 (59,358,895 to 59,371,714, forward strand). Ensembl gene ENSG00000176495.
Subcellular location: Cell membrane
Pathways (Reactome):
Sensory Perception: Expression and translocation of olfactory receptors
Gene Ontology:
Molecular function: G protein-coupled olfactory receptor activity; odorant binding; olfactory receptor activity; G protein-coupled receptor activity
Biological process: detection of chemical stimulus involved in sensory perception; detection of chemical stimulus involved in sensory perception of smell; adenylate cyclase-activating G protein-coupled receptor signaling pathway; sensory perception of smell; G protein-coupled receptor signaling pathway
Cellular component: membrane; plasma membrane
Genetic constraint (gnomAD): Loss-of-function variants: 0 observed, 0.25 expected, observed/expected ratio (o/e) 0, 90% interval 0 to 1.87. That is too few expected variants to judge how well the gene tolerates losing a copy. Missense variants: 474 observed, 385.49 expected, observed/expected ratio (o/e) 1.23, 90% interval 1.14 to 1.33. Synonymous variants: 166 observed, 137.86 expected, observed/expected ratio (o/e) 1.2, 90% interval 1.06 to 1.37.
Homologues: Orthologues: chimpanzee OR5AN1 (99% identical), macaque OR5AN1 (97% identical), mouse Or5an1 (82% identical), mouse Or5an1c (81% identical), mouse Or5an1b (80% identical), rat Or5an1 (80% identical), rat Or5an1b (80% identical), mouse Or5an9 (79% identical), rat Or5an10 (79% identical), mouse Or5an10 (79% identical), mouse Or5an11 (79% identical), rat Or5an9 (78% identical), and 5 more. Paralogues in human: OR5A2 (58% identical), OR5A1 (57% identical), OR5F1 (52% identical), OR8I2 (50% identical), OR5D18 (49% identical), OR5AP2 (49% identical), OR5P3 (49% identical), OR8B4 (49% identical), OR5B12 (48% identical), OR5I1 (48% identical), OR8B2 (48% identical), OR8B3 (48% identical), and 84 more.